NEFL (neurofilament light chain)
Diseases named in the same sentence as NEFL in open-access papers (continued):
Sharing a sentence is not in itself a finding about the gene and the disease.
dementia (360 papers, 2008 to 2026). Loss of intellectual abilities interfering with an individual's social and occupational functions. "In older adults, ACE exposure is associated with poorer cognitive performance and less favorable neuroimaging profiles, as well as plasma biomarkers related to dementia risk, including serum neurofilament light chain (NfL), glial markers, and cytokine panels." (PMID 41303499, 2025). "Anticholinergic drugs (ACDs) and the neurodegeneration biomarker neurofilament light chain (NfL) are associated with dementia; however, the interplay between anticholinergic drug exposure and neurodegeneration in dementia risk remains underexplored." (PMID 41373116, 2025). "Blood creatinine levels are associated with the blood biomarkers for neurodegeneration, including neurofilament light chain(NFL), amyloid protein, and phosphorylated tau, as well as the risk of dementia." (PMID 40095208, 2025). "Over recent years, circulating neurofilament light chain and glial fibrillary acidic protein have been independently and jointly associated with dementia risk." (PMID 39175459, 2025). "Future research should also investigate the combined predictive value of LCN2 alongside other dementia‐related blood biomarkers, such as neurofilament light chain (NfL), to enhance diagnostic accuracy." (PMID 40365739, 2025). "Significant predictions of dementia risk associated with plasma p‐tau181, neurofilament light chain (NfL), and SCI." (PMID 38421124, 2024). "Neurofilament light chain (NfL) is a promising biomarker for risk stratification and disease monitoring of dementia, but its utility in the preclinical disease stage remains uncertain." (PMID 37535203, 2024). "This ratio is outperformed by other biomarkers (such as neurofilament light chain (NfL) or phospho-tau 217 (pTau217) for discriminating between cognitive impairment due to AD and other causes of dementia." (PMID 38047367, 2023). "Elevated neurofilament light chain (NfL) levels have been associated with dementia in idiopathic Parkinson’s disease (iPD)." (PMID 37699957, 2023). "Biomarkers linked to dementia neuropathology (e.g., hyperphosphorylated tau, amyloid beta), neuronal injury (e.g., total tau, neurofilament light chain), glial activation (e.g., glial fibrillary acidic protein), and systemic inflammation (e.g., interleukin-6) have shown promise." (PMID 40951922, 2025). "Among them, peripheral glial fibrillary acidic protein (GFAP) and neurofilament light chain (NfL) have gained much traction for their ability to predict the risk of dementia in individuals with subjective cognitive decline and mild cognitive impairment, as well as dementia-specific mortality." (PMID 38735950, 2024). "In the current study, we raised the hypothesis that immunoglobulin levels are associated with early markers of dementia, including neurofilament light chain (NfL), t-tau, and Aβ, as well as structural markers on neuroimaging." (PMID 37936180, 2023). "Neurofilament light chain (NfL) has emerged as a significant diagnostic and prognostic marker with elevated levels in CSF and blood of FTD compared to healthy controls and other dementias." (PMID 39940966, 2025). "Plasma biomarkers in dementia showed higher amyloid beta 40, phosphorylated tau181, neurofilament light chain, and tumor necrosis factor alpha levels." (PMID 41085166, 2025). "The eXtreme Gradient Boosting machine learning algorithm also identified RPS6KB1, NEFL, and KIM1 as the most important protein features for predicting future all-cause dementia." (PMID 40092369, 2025). "Recently, neurofilament light chains (NFL), which form crucial intermediate filaments for neuron assembly, have been investigated to distinguish dementias and autoimmune mediated encephalitis from primary psychiatric disorders." (PMID 40754554, 2025). "Neurofilament light chain (NfL) has been proven as a potential biomarker in neurodegenerative disease, including dementia." (PMID 38627748, 2024).
dementia (continued). "The neurofilament light chain (NfL) is another molecule that has been analyzed in the context of AD as a progression biomarker or predictor for dementia, even more helpful in other pathologies, such as FTLD." (PMID 36674742, 2023). "Currently, CSF and positron emission tomography (PET) biomarkers, including Aβ, tau, and neurofilament light chain (NfL), are employed for the prediction of dementia onset and progression from mild cognitive impairment (MCI) to AD." (PMID 38003448, 2023). "Accordingly, new CSF biomarkers (e.g. neurofilament light chain and neurogranin) have been used to optimize dementia diagnoses." (PMID 34816970, 2022). "In particular, serum neurofilament light chain (NfL), a structural neuronal intermediate filament, has evolved as a promising biomarker in pre-clinical and clinical dementia." (PMID 36217177, 2022). "Neurofilament light chain (NFL) level has been suggested as a blood-based biomarker for neurodegeneration in dementia." (PMID 34996525, 2022). "Neurofilament light chain protein (NfL) in cerebrospinal fluid (CSF) reflects the severity of neurodegeneration, with its altered concentrations discovered in Parkinson’s disease (PD) and Parkinson’s disease dementia (PD-D)." (PMID 36589544, 2022). "In fact, a recent longitudinal study from the BioFINDER and ADNI cohorts reported that a model including plasma neurofilament light chain and p-tau181 was associated with superior prediction of clinical progression from MCI to dementia." (PMID 34222875, 2021). "In the same study, however, the neurofilament light chain protein (NFL), a CSF biomarker of axonal injury, predicted dementia development." (PMID 20525234, 2010). "Among the top 20 proteins in the brain aging clock, those associated with at least two dementia phenotypes included glial fibrillary acidic protein (GFAP), neurofilament light chain polypeptide (NEFL), brevican (BCAN), kallikrein-6 (KLK6) and synaptotagmin-1 (SYT1)." (PMID 41299092, 2026). "Finally, fluid biomarkers of neurodegeneration, including neurofilament light chain (NfL) and total tau (t-tau), are gaining traction as dynamic indicators of neuronal injury in both pain and dementia contexts." (PMID 41373439, 2025). "This suggests plasma biomarkers, especially neurofilament light chain, could be valuable for early dementia detection." (PMID 39749011, 2025). "Neurofilament light chain (NfL), a subunit of neurofilaments abundant in neuronal axons, is a non-invasive blood-based biomarker for detecting or predicting neurodegeneration and clinical progression in preclinical or prodromal stage of dementia." (PMID 39267169, 2024). "Neurofilament light chain (NfL), a non-specific marker of neuronal injury has been associated with the risk of AD, vascular dementia, and other types of dementia (e.g. Frontal temporal lobe dementia." (PMID 39350363, 2024). "Interestingly, six proteins (NEFL, WNT9A, IL17D, IGFBP2, KLK4, and PGF) were repeatedly selected in both diagnostic models that classified dementia from both cognitively normal controls and MCI." (PMID 37175824, 2023). "For dementia, NEFL, BCAN, GFAP, and GDF15 were the main proteins influencing disease risk." (PMID 38016990, 2023). "Furthermore, neurofilament light chain (NfL) as a marker for neuronal damage has gained attention in predicting pre-clinical and clinical dementia." (PMID 36142218, 2022). "Plasma neurofilament light chain (NfL) is one of the established biomarkers of AD, suggesting that it may be useful as an indicator of dementia in DS patients." (PMID 30951523, 2019). "Neurofilament light chain (NfL) is a cytoskeleton protein expressed in large-caliber myelinated axons and is a potential blood biomarker for axonal degeneration in various neurological diseases, such as dementia, multiple sclerosis, and acquired peripheral neuropathies." (PMID 36059704, 2022).
dementia (continued). "Notably, NEFL, WNT9A, IL17D, IGFBP2, KLK4, and PGF proteins were included in both models that differentiated dementia from either cognitively normal controls or MCI." (PMID 37175824, 2023). "Seventeen proteins had more than a 50% difference between subjects with dementia and controls, including VIM (2.2 fold increase), NTproBNP (2.2 fold increase), CHIT1 (2.2 fold increase), NEFL (1.7 fold increase), ENPP7 (1.6 fold decrease), and FCGR2A (1.5 fold decrease)." (PMID 37175824, 2023). "We did not have data available on other identified markers of dementia at examination cycle seven to include in our analyses, e.g., phosphorylated tau species such as p-tau181 and p-tau217, neurofilament light chain (NFL), or glial fibrillary acidic protein (GFAP)." (PMID 35563811, 2022). "Three of these proteins, neurofilament light polypeptide (NEFL), acetylcholinesterase (ACHE), and pTau181 were uniquely upregulated in participants with dementia and not in MCI participants." (PMID 39649596, 2024).
Cognitive impairment (297 papers, 2014 to 2026). Abnormal cognition is characterized by deficits in thinking, reasoning, or remembering. "Both frailty and elevated serum neurofilament light chain (sNfL) levels are linked to cognitive impairment." (PMID 39463817, 2024). "Neurofilament light chain (NFL) is an established marker of neuronal injury associated with cognitive impairment in PWH." (PMID 38257772, 2023). "Existing studies have shown that molecular biomarkers such as homocysteine (Hcy), High-sensitivity C-reaction protein (hs-CRP), Lipoprotein-Associated Phospholipase A2, and neurofilament light chain (NfL), may be strongly associated with cognitive impairment in CSVD." (PMID 39839309, 2024). "Increasing plasma neurofilament light chain and glial fibrillary acidic protein levels are biomarkers of incident cognitive impairment among participants with type 2 diabetes and overweight or obesity." (PMID 39913137, 2025). "Surprisingly, subtle cognitive impairments as well as axonal damage, indicated by elevated serum neurofilament light chain (sNfL), prevail in CIDP." (PMID 40459587, 2025). "Neurofilament light chain (NFL) is indicative of neurodegeneration, and elevated plasma NFL levels are associated with cognitive deficits and AD-related brain atrophy." (PMID 38994939, 2024). "This study investigated the effects of inflammation on cognitive integrity in patients with cognitive impairment through the functional interaction of plasma neurofilament light chain (NFL) with large‐scale brain networks." (PMID 37545369, 2023). "Serum neurofilament light chain (sNfL) level, which is a biomarker indicative of neuroaxonal damage and cognitive impairment, has been reported in several neurological diseases." (PMID 37435483, 2023). "The proteins associated with these neuroprotective effects (HTT, NEFH and NEFL) are potential drug targets for the treatment of obesity-induced cognitive impairment with semaglutide." (PMID 36998046, 2023). "This study aimed to assess the level of peripheral blood neurofilament light chain (NfL) and total tau (t-tau) protein in AD patients and investigate their relationship with cognitive impairment." (PMID 36937471, 2023). "The purpose of this research was to examine the relationship between plasma neurofilament light chain (pNfL) and cognitive impairment following a posterior circulation stroke." (PMID 35800005, 2022). "Blood-based assays for detecting pathologic protein, such as amyloid beta (Aβ), total tau protein, and neurofilament light chain (NfL), have the advantages of being less invasive and more cost-effective for diagnosing patients with cognitive impairment." (PMID 34122041, 2021). "Studies have also shown an association between cerebrospinalfluid (CSF) biomarker and progression of cognitive impairment in PD, which mainly focus on Aβ 42, t-tau, p-tau, α-synuclein, and neurofilament light chain (NFL)." (PMID 32269747, 2020). "In this study, we tested the level of peripheral blood neurofilament light chain (NfL) in VaD patients and explored its relationship with cognitive impairment." (PMID 33204362, 2020). "C9-149R mice exhibited reduced body weight and subtle behavioral alterations without robust motor deficits, whereas TDP-43Q331K mice developed pronounced, progressive motor and cognitive impairments accompanied by a ~7-fold elevation in plasma neurofilament light chain (NfL)." (PMID 41751955, 2026). "Clinical evidence shows that kynurenine metabolite ratios correlate with plasma neurofilament light chain, cognitive deficits, obesity-related inflammation, and phenotype-specific exercise responsiveness, underscoring KP plasticity as a potential determinant of disease trajectory." (PMID 42266250, 2026). "Sensitivity analysis of neurofilament light chain levels suggested that malignant tumors may contribute to the development of mild cognitive impairment (aOR: 1.52; 95% CI: 1.01–2.27; p = 0.044)." (PMID 41236360, 2025).
Cognitive impairment (continued). "Additionally, some research explored potential biomarkers, such as the Cerebellar Cognitive Affective Syndrome Scale (CCAS‐S) and neurofilament light chain, to assess cognitive impairments and monitor disease progression." (PMID 40657683, 2025). "Additionally, axonal damage reflected by circulating neurofilament light chain (NfL) has been correlated with cognitive impairment." (PMID 40645956, 2025). "The neurofilament light chain (NfL) protein has emerged as a key biomarker, showing strong positive correlations with cognitive impairment, neurodegeneration, hypoxic brain injury, and cardiac disease, and elevated NfL levels have also been significantly associated with lower cognitive performance." (PMID 40427605, 2025). "Differential associations of hippocampal volume (HV), 18F‐fluorodeoxyglucose positron emission tomography (FDG PET) standardized uptake value ratios (SUVRs), and plasma neurofilament light chain (NfL) levels with amyloid beta (Aβ)–tau pathology and cognitive impairment were examined." (PMID 39989286, 2025). "Additionally, glucose hypometabolism – along with elevated plasma neurofilament light chain level – was related to more severe cognitive impairment in Aβ− subjects." (PMID 37381042, 2023). "Thus, we sought to determine the prognostic utility of serum neurofilament light chain levels alone and in combination with MRI markers by examining their ability to predict cognitive impairment in early multiple sclerosis." (PMID 35813883, 2022). "Among them, α-synuclein (α-syn), total and p-Tau, Aβ-40 and 42, and neurofilament light chain (NfL) are most commonly investigated and may contribute to brain atrophy and cognitive impairment." (PMID 34442345, 2021). "We also aimed to examine the association between WMH burden and both GM atrophy and cognitive deficits in FTD, as well as the association with fluid markers of axonal damage (neurofilament light chain, NfL) and astrocytosis (glial fibrillary acidic protein, GFAP)." (PMID 31835286, 2019). "In this cross-sectional study of 1144 participants, including individuals with and without cognitive impairment, higher levels of PA were significantly associated with lower levels of plasma neurofilament light chain and phosphorylated tau-217 and better cognition." (PMID 40042844, 2025). "Increasing neurofilament light chain and glial fibrillary acidic protein levels, but not change in the amyloid-β42/40 ratio or phosphorylated tau 181, were associated with worsening cognitive function and incident cognitive impairment." (PMID 39913137, 2025). "Cognitive impairment outcomes by baseline category of WMH and plasma total tau and neurofilament light chain (NfL)." (PMID 39229896, 2024). "Here, we investigated plasma Glial Fibrillary Acidic Protein (GFAP), Neurofilament Light Chain (NfL) and Phosphorylated-tau-181 (pTau 181) in AD and in its early stages: Subjective cognitive decline (SCD) and Mild cognitive impairment (MCI)." (PMID 38654932, 2024). "Among those, the neuroaxonal injury marker neurofilament light chain (NfL) was identified to potentially serve as a prognostic biomarker for SAE and to predict long-term cognitive impairment." (PMID 37259091, 2023). "Cognitive impairment has been described in patients 7 months after SARS-CoV-2 infection and increased markers of neurodegenerative processes involving total serum tau, phosphorylated tau, and neurofilament light chain have been detected in patients with COVID-19." (PMID 38674105, 2024). "In attempts to explain this finding, neurodegenerative biomarkers like neurofilament light chain (NfL) and glial fibrillary acidic protein (GFAP) were measured and found to be higher in COVID-19 patients than non-COVID-19 patients with mild cognitive impairment or AD." (PMID 39456822, 2024).